CXCL8 (C-X-C motif chemokine ligand 8)
Diseases named in the same sentence as CXCL8 in open-access papers (continued):
Sharing a sentence is not in itself a finding about the gene and the disease.
age-related macular degeneration (10 papers, 2009 to 2026). Age-related loss of vision in the central portion of the retina (macula), secondary to retinal degeneration. "Finally, polymorphisms in the promoter regions of CXCL8, the gene that encodes IL-8, are associated with DR susceptibility, as well as with susceptibility to other angiogenic conditions such as cancer and age-related macular degeneration (AMD)." (PMID 41176546, 2025).
appendicitis (10 papers, 2011 to 2025). Acute inflammation of the vermiform appendix. "Most studies have observed higher circulating CXCL8 levels in patients with appendicitis, and the inflamed appendix is known to locally express elevated CXCL8." (PMID 27417541, 2016).
cerebral malaria (10 papers, 2012 to 2024). A sequestration of Plasmodium falciparum in the brain, which can cause coma and/or seizures. "Other studies have shown that circulating levels of CXCL8 and CCL4 correlated with parasite density, and when found in the cerebrospinal fluid they can predict cerebral malaria mortality." (PMID 39830896, 2024). "However, future analysis is necessary to confirm or investigate this hypothesis, mainly by evaluating the production levels of CCL2, CCL4, CXCL4, CXCL8, CXCL10, and the receptors CXCR3 and CCR2, correlated with susceptibility to cerebral malaria and lung inflammation." (PMID 38256880, 2023).
cholangiocarcinoma (10 papers, 2017 to 2026). A carcinoma that arises from the intrahepatic biliary tree (intrahepatic cholangiocarcinoma) or from the junction, or adjacent to the junction, of the right and left hepatic ducts (hilar cholangiocarcinoma). "Notably, VEGFA and CXCL8 exhibited higher protein expression in HCC and cholangiocarcinoma tumor tissues compared with normal liver tissue." (PMID 41514936, 2026).
myelofibrosis (10 papers, 2013 to 2025). A partial or complete replacement of the bone marrow stroma by fibrous tissue. "The inhibition of CXCL8/CXCR2 presents a promising therapeutic opportunity for intercepting the progression of myelofibrosis in myeloproliferative neoplasms." (PMID 39706835, 2024). "A major role for human (h)CXCL8 (interleukin-8) in the pathobiology of myelofibrosis (MF) has been suggested by observations indicating that MF megakaryocytes express increased levels of hCXCL8 and that plasma levels of this cytokine in MF patients are predictive of poor patient outcomes." (PMID 35392239, 2022). "This underscores the importance of CXCL8/CXCR2 in fibrosis progression and suggests that inhibiting this pathway could be a promising therapeutic strategy for managing myelofibrosis." (PMID 38972952, 2024).
neurosyphilis (10 papers, 2016 to 2026). Infection of the brain or spinal cord by Treponema pallidum. "In conclusion, our data show that CXCL13, CXCL10 and CXCL8 are potential biomarkers to be used as a complementary diagnostic tool for neurosyphilis." (PMID 27650493, 2016). "ROC curve analysis revealed areas under the curve (AUC) for CSF CXCL8 and CSF TP distinguishing neurosyphilis from syphilis of 0.766 and 0.830, respectively." (PMID 42317354, 2026). "Binary logistic regression analysis identified CSF CXCL8 and CSF TP as independent predictors of neurosyphilis." (PMID 42317354, 2026). "The levels of CXCL13, CXCL10 and CXCL8 in the AH of patients with neurosyphilis are similar to previously reported levels in the CSF of patients with neurosyphilis and can potentially be an adjunct in the diagnosis of ocular syphilis." (PMID 38983560, 2022). "They found that CXCL13, CXCL10 and CXCL8 levels were significantly increased in the neurosyphilis group." (PMID 38983560, 2022). "The sensitivity/specificity of CXCL13, CXCL10, and CXCL8 in the diagnosis of neurosyphilis were 85.4/89.1%, 79/90.1%, and 79.6/91.1%, respectively." (PMID 36452956, 2022). "CXCL13, CXCL10 and CXCL8 showed AH levels equivalent to previously reported levels in the CSF of patients with neurosyphilis and can potentially be an adjunct in the diagnosis and management of ocular syphilis." (PMID 38983560, 2022). "The concentrations of CXCL13, CXCL10, and CXCL8 were increased in the CSF of neurosyphilis patients, which was related to the CSF protein concentration and the CSF-VDRL titer." (PMID 36452956, 2022). "The levels of CCL24 (P = .0185), CXCL7 (P < .0001), CXCL13 (P < .0001), CXCL10 (P < .0001), and CXCL8 (P < .0001) in the CSF of neurosyphilis patients were higher than those in the CSF of patients without neurosyphilis." (PMID 32419252, 2020). "The increased CSF levels of CCL24, CXCL7, and CXCL8 require further investigation to elucidate the role of eosinophils and neutrophils in neurosyphilis." (PMID 32419252, 2020). "Given the measurements were correlated with the disease activity, we therefore investigated the correlation between CSF CXCL13, CXCL10 and CXCL8 levels and these measurements in neurosyphilis patients." (PMID 27650493, 2016). "As the diagnostic biomarkers, the AUCs of CSF CXCL10 and CXCL8 levels and the CSF/serum CXCL10 ratio were more than or approximate to 0.9 for all untreated neurosyphilis patients, though they were lower than that of CSF VDRL." (PMID 27650493, 2016). "The CSF/serum ratio of CXCL8 (median 33.59, ranged from 0.51 to 220.1) in neurosyphilis patients was significantly higher than that in non-neurosyphilis patients (median 6.1, ranged from 0.02 to 43.3, p = 0.000)." (PMID 27650493, 2016). "The AUC of Model 1 was higher than that of CSF CXCL10, CXCL8 for all neurosyphilis (p = 0.0165, p < 0.0001, respectively) and for asymptomatic neurosyphilis (p = 0.0363, p = 0.0047, respectively)." (PMID 27650493, 2016). "In addition, the decrease in the CSF levels of CXCL10 and CXCL8 was consistent with the decrease of CXCL13 levels after treatment for neurosyphilis was initiated." (PMID 38983560, 2022). "Given the marked elevation of CSF CXCL13, CXCL10 and CXCL8 as well as CSF/serum ratio of these chemokines in neurosyphilis patients, we further evaluated these chemokines as biomarkers in neurosyphilis diagnosis using the receiver operating characteristic (ROC) curve analysis." (PMID 27650493, 2016). "Thus, we assessed the efficacy of combined CSF CXCL13, CXCL10 and CXCL8 (Model 1) and combined the ratio of CSF/serum CXCL13, CXCL10 and CXCL8 (Model 2) as biomarkers for diagnosis of neurosyphilis." (PMID 27650493, 2016). "Above these values CSF CXCL13 was 85.4% sensitive and 89.1% specific for diagnosing neurosyphilis, and CXCL10 and CXCL8 were both 79% sensitive, with a specificity of 90.1% and 91.1%, respectively." (PMID 38983560, 2022).
neurosyphilis (continued). "The AUCs of CSF CXCL13, CXCL8, and CXCL10 were all approximately 0.9 in a previous study, indicating that these chemokines are not only potential biomarkers as complementary diagnostic tools for neurosyphilis but may also be useful for monitoring therapeutic effects." (PMID 32419252, 2020). "CXCL13 and CXCL8/IL-8 have been already studied (individually and in combination with IL-12p40 or CXCL10) in the context of MS and neurosyphilis." (PMID 31356620, 2019). "The corresponding sensitivities/specificities of CSF CXCL13, CXCL8,CXCL10 and the CSF/serum ratio of CXCL13, CXCL8,CXCL10 in diagnosis of neurosyphilis were 85.4%/89.1%, 79%/90.1% and 79.6%/91.1%, 86.6%/99%, 79%/73.3% and 86%/92.1%, respectively." (PMID 27650493, 2016). "The area under the ROC curve (AUC) of CSF CXCL13, CXCL8,CXCL10 and the CSF/serum ratio of CXCL13, CXCL8,CXCL10 in the diagnosis of neurosyphilis were 0.940, 0.899, 0.915, 0.963, 0.846 and 0.926, respectively." (PMID 27650493, 2016). "In our study, the levels of CSF CXCL8 and CXCL10 were increased in neurosyphilis patients, especially in symptomatic neurosyphilis patients." (PMID 27650493, 2016). "We hope to further evaluate the specificity of CXCL13, CXCL10 and CXCL8 in the diagnosis of neurosyphilis, so that NS can be independently diagnosed without interference from other factors." (PMID 41221293, 2025). "Elevated concentrations of CXCL8, CXCL10, and IL-10 may also be potential biological markers of neurosyphilis, especially asymptomatic neurosyphilis." (PMID 38105236, 2023). "Our findings also show that the analysis of the chemokines CXCL13, CXCL10 and CXCL8 in the CSF can indicate the occurrence of neuroinflammation in patients who do not meet the criteria for being diagnosed with neurosyphilis." (PMID 38983560, 2022). "Firstly, it shows that the chemokines measured in the AH of patients with ocular syphilis correlate to the values previously found in the CSF of patients with neurosyphilis, and that patients with ocular syphilis have elevated CSF levels of CXCL13, CXCL10 and CXCL8, as expressed in the mean values." (PMID 38983560, 2022). "The mean AH concentrations of CXCL8 in participants without neurosyphilis were also higher than serum concentrations in participants both with and without neurosyphilis." (PMID 38983560, 2022). "In patients with ocular syphilis and neurosyphilis the AH/serum ratios for CXCL13, CXCL10 and CXCL8 were consistently higher than those in patients with ocular syphilis but no neurosyphilis." (PMID 38983560, 2022). "The mean AH concentrations of CXCL8 in participants who were not diagnosed with neurosyphilis were higher than the serum concentrations in participants both with and without neurosyphilis." (PMID 38983560, 2022). "The HIV-positive group had higher levels of CXCL13, CXCL10 and CXCL8, but this was not statistically influenced by the neurosyphilis status in these patients with ocular syphilis." (PMID 38983560, 2022). "Antibody array analysis showed that the CSF levels of CCL24 (P = .0185), CXCL7 (P < .0001), CXCL13 (P < .0001), CXCL10 (P < .0001), and CXCL8 (P < .0001) were significantly higher in patients with than without neurosyphilis." (PMID 32419252, 2020). "In the search for biomarkers of neurosyphilis, we investigated the chemokine profile in CSF of neurosyphilis patients and found that the concentrations of CXCL13, CXCL10 and CXCL8 were selectively elevated in neurosyphilis patients and correlated with CSF protein concentration and CSF-VDRL titer." (PMID 27650493, 2016). "Our results suggest that the elevated concentrations of CXCL13, CXCL8, and CXCL10 or their increasing CSF/serum ratios may be potential biomarkers of neurosyphilis, particularly for asymptomatic neurosyphilis." (PMID 27650493, 2016).
neurosyphilis (continued). "The AUC of Model 2 was not statistically different from that of the ratio of CSF/serum CXCL13 and CSF VDRL (p = 0.3968, p = 0.1386, respectively), but it was higher than that of the ratio of CSF/serum CXCL8 and CXCL10 (p < 0.0001, p = 0.007, respectively) for all neurosyphilis." (PMID 27650493, 2016). "The levels of CSF CXCL10 and CXCL8 positively correlated with the CSF-VDRL titer and CSF protein concentration in neurosyphilis patients, indicating that CXCL8 and CXCL10 may be involved in the inflammatory process in neurosyphilis patients." (PMID 27650493, 2016). "In patients with ocular syphilis and neurosyphilis the AH/serum ratio for CXCL13, CXCL10 and CXCL8 was 3.78, 89.72 and 24.92 respectively while in patients with ocular syphilis without neurosyphilis the AH/serum ratio for CXCL13, CXCL10 and CXCL8 was 2.82, 76.89 and 14.04 respectively." (PMID 38983560, 2022). "The serum CXCL8 level was higher in non-neurosyphilis patients than that in neurosyphilis patients (p = 0.006), and was also higher in asymptomatic neurosyphilis patients than that in symptomatic neurosyphilis patients (p = 0.004)." (PMID 27650493, 2016). "We found that the levels of CXCL13, CCL24, CXCL8, CXCL10, and CXCL7 were significantly higher in the CSF of those with than those without neurosyphilis." (PMID 32419252, 2020). "Consistent with the antibody array data, the levels of CSF CXCL13, CXCL8 and CXCL10 were 45.9 (ranged from 0.09 to 341.42), 4.3 (ranged from 0.43 to 31.96), 7.2 (ranged from 0.37 to 67.16) fold higher in neurosyphilis patients than those in non-neurosyphilis patients, respectively." (PMID 27650493, 2016).
non-alcoholic steatohepatitis (10 papers, 2020 to 2025). "KEGG enrichment analysis revealed an enrichment of the NAFLD pathway, suggesting that SLXG may potentially treat nonalcoholic steatohepatitis (NASH) by regulating the expression of genes such as CXCL8, AKT1, SREBF1, IL6, PPARA, and ADIPOQ." (PMID 39928768, 2025).
pancreatic adenocarcinoma (10 papers, 2014 to 2026). "The aim of our research was to investigate the role of macrophage migration inhibitory factors (MIFs), interleukin-8 (IL-8/CXCL8), and stem cell factors (SCFs) in pancreatic adenocarcinoma." (PMID 42122077, 2026).
adenovirus infection (9 papers, 2017 to 2023). "Moreover, the expression of CXCL8 induced the relocalization of the viral receptor CAR, as well as of ανβ3 integrins to the apical side of the epithelial cells, thus contributing to adenovirus infection." (PMID 32872518, 2020).
airway hyperresponsiveness (9 papers, 2008 to 2025). "Neutrophils also secrete cytokines and chemokines, such as IL-1β, TNF-α, CXCL8 (IL-8), and GM-CSF, which further enhance the inflammatory response leading to chronic inflammation, airway hyperresponsiveness and, in a longer perspective, airway remodeling." (PMID 41156007, 2025).
apical periodontitis (9 papers, 2013 to 2026). "This species can activate osteoclasts and induce an inflammatory response in experimental apical periodontitis, stimulating the production of chemokines such as CXCL8 by periodontal ligament fibroblasts as well as the maturation of dendritic cells." (PMID 39125663, 2024).
Arrhythmia (9 papers, 2015 to 2026). Any cardiac rhythm other than the normal sinus rhythm. "However, the involvement of other genes, including CXCL8, FOS, CCL2, and MMP9, in aconitine-induced arrhythmias warrants further research." (PMID 35915792, 2022).
Behcet disease (9 papers, 2011 to 2023). A chronic, relapsing, multisystemic vasculitis characterized by mucocutaneous lesions, as well as articular, vascular, ocular and central nervous system manifestations. "Type IVd reactions cause tissue damage due to the production of CXCL-8 (IL-8) by T lymphocytes, which promotes the recruitment of neutrophils to sites of inflammation (e.g., Behçet’s disease)." (PMID 37233255, 2023).
Chlamydia infection (9 papers, 2012 to 2025). "Neutrophils are recruited to the site of infection by epithelial cells that secrete pro-inflammatory cytokines and chemokines during Chlamydia infection, such as IL-8 (also called chemokine (C-X-C motif) ligand 8 (CXCL8)), IL-6, CXCL1, CXCL2, and CXCL5." (PMID 40005489, 2025).
glomerulonephritis (9 papers, 2012 to 2023). A renal disorder characterized by damage in the glomeruli. "Inflammatory processes in glomerulonephritis strongly depend on the pro-inflammatory chemokines CXCL8 (interleukin-8 (IL-8)), CCL2 (monocyte chemotactic protein-1 (MCP-1)) and CXCL2 (macrophage inflammatory protein-2α (MIP-2α)) to direct neutrophils and macrophages towards the glomerulus." (PMID 30248108, 2018).
Hypercholesterolemia (9 papers, 2012 to 2025). An increased concentration of cholesterol in the blood. "Emerging evidence indicates that the plasma levels of some platelet chemokines, such as CXCL4, CCL5, CXCL5, CXCL1, CCL2 and CXCL8, are increased in hypercholesterolemia." (PMID 27933092, 2016). "In hypercholesterolemia, surface-adherent platelets express CXCL8 or CCL2 to recruit leukocytes, which adhere to the denuded artery and contribute to neointimal lesion formation." (PMID 27933092, 2016). "Our study is the first to show the long-term effects of purified anthocyanins on CXCL8 and CCL2 in Chinese individuals with hypercholesterolemia." (PMID 27933092, 2016).
intrahepatic cholangiocarcinoma (9 papers, 2023 to 2025). A carcinoma that arises from the intrahepatic bile duct epithelium in any site of the intrahepatic biliary tree. "Liu et.al recently revealed that METTL1-mediated m7G modification significantly regulates PMN-MDSCs accumulation in the immune microenvironment and intrahepatic cholangiocarcinoma progression through targeting CXCL8 in humans and Cxcl5 in mice." (PMID 39440054, 2024). "CXCL8 in human and Cxcl5 in mouse are key translational targets of METTL1 that facilitate its function in promoting PMN-MDSC accumulation in tumor immune microenvironment of intrahepatic cholangiocarcinoma." (PMID 40443650, 2025). "Moreover, METTL1 upregulates the expression of chemokines CXCL5 and CXCL8 in an m7A-dependent manner, leading to MDSCs accumulation and immunosuppression in HCC and intrahepatic cholangiocarcinoma (ICC)." (PMID 38902779, 2024). "In a preclinical mouse model of intrahepatic cholangiocarcinoma (ICC), PD-1 treatment simultaneously blocked METTL1 and its downstream chemokine pathway (CXCL8 in the human body and CXCL5 in the mouse body), boosting the immune response in the mice." (PMID 39155349, 2024).
keratoconus (9 papers, 2016 to 2025). A degenerative, structural disorder of the eye, characterized by a cone-shaped protrusion of the cornea. "In the current study, we have determined the associations between nine mediators (IL-6, IL-10, CXCL8/IL-8, CCL5/RANTES, MMP-9, MMP-13, TIMP-1, t-PA, and PAI-1) in the tear fluid of keratoconic patients covering the whole spectrum of the disease (from subclinical to manifest keratoconus)." (PMID 26881061, 2016). "Additionally, elevated levels were detected in inflammatory ocular surface diseases as well as in keratoconus, and CXCL8, which is the predominant chemoattractant in the tear fluid, was significantly lower both in PMD and KC than in the controls in our study." (PMID 27074131, 2016).
mesothelioma (9 papers, 2015 to 2025). A usually malignant and aggressive neoplasm of the mesothelium which is often associated with exposure to asbestos. "Their expression was confirmed in MM cell lines after miR-503 inhibition, while in human mesothelioma tissues we found a reverse expression only for CXCL8, Serpine1, and SPP1 compared to the cells." (PMID 39984959, 2025). "However, in vivo analysis on human mesothelioma samples confirmed a reverse expression of CXCL8, SERPINE1, and Osteopontin, while the expression values were not confirmed for the remaining genes." (PMID 39984959, 2025).